KRAS (KRas proto-oncogene, GTPase)
Diseases named in the same sentence as KRAS in open-access papers (continued):
Sharing a sentence is not in itself a finding about the gene and the disease.
gastric cancer (continued). "For example, BRAF, KRAS, and PIK3CA, a set of rarely identified mutations in sporadic gastric cancers, have recently been reported in the microsatellite subsets of cancer." (PMID 25025766, 2014). "In human oncology, the importance of the EGFR/HER-2/KRAS signalling pathway in gastric cancer is well established, and HER-2 testing is required before initiating therapy." (PMID 24454858, 2014). "In human oncology, the importance of the EGFR/HER-2/KRAS signalling pathway in gastric cancer is well established." (PMID 24454858, 2014). "Integrative analysis and de novo assemblies revealed the architecture of a wild-type KRAS amplification, a common driver event in gastric cancer." (PMID 23237666, 2012). "Results indicate that NVP-BKM120, a pan-class I PI3K inhibitor, is able to inhibit mTOR downstream activation, but induces the phosphorylation of AKT and the activation of p-ERK or p-STAT3 in KRAS mutant gastric cancer cells." (PMID 22159814, 2012). "In gastric cancer, genetic mutation/amplification of PIK3CA, AKT1 and KRAS, and loss of heterozygosity of PTEN have been recognized so far." (PMID 22159814, 2012). "Intriguingly, single treatment of NVP-BKM120 induced an alternate pathway in KRAS mutant gastric cancer cell lines in a cell line-specific manner." (PMID 22159814, 2012). "In KRAS mutant gastric cancer cells, either p-ERK or p-STAT3 was also increased upon treatment of NVP-BKM120." (PMID 22159814, 2012). "Gastric cancer cell lines with wildtype KRAS amplification show constitutive KRAS activation and sensitivity to KRAS RNAi knockdown." (PMID 21781349, 2011). "Gene amplification coincided with intense KRAS immunoreactivity in the same tumor samples, which suggested that gene amplification results in the overexpression of the KRAS in primary gastric cancer." (PMID 19545448, 2009). "We next investigated the levels of KRAS mRNA in KRAS-amplified gastric cancer cells by quantitative real-time RT-PCR (qRT-PCR)." (PMID 19545448, 2009). "We demonstrated that gene amplification likely forms the molecular basis of overactivation of KRAS in gastric cancer." (PMID 19545448, 2009). "To determine the role of KRAS in primary gastric cancer, we used qPCR to analyze KRAS amplification in genomic DNA derived from primary gastric cancer specimens." (PMID 19545448, 2009). "DGS of gastric cancer cell lines detected the amplification of the KRAS locus on chromosome 12p12.1." (PMID 19545448, 2009). "DGS analysis of the HSC45 gastric cancer cell line revealed the amplification of a 500-kb region on chromosome 12p12.1, which contains the KRAS gene locus." (PMID 19545448, 2009). "Using DGS, we investigated the role of KRAS gene amplification in the overactivation of KRAS in gastric cancer." (PMID 19545448, 2009). "Amplification of the KRAS locus was detected in 15% (3/20) of gastric cancer cell lines (8–18-fold amplification) and 4.7% (4/86) of primary gastric tumors (8–50-fold amplification)." (PMID 19545448, 2009). "Concurrent KRAS and APC variants are uncommon in gastric cancer." (PMID 40916582, 2025). "MSigDB hallmark analysis (E–F) identified pathways like KRAS signaling up, mTORC1 signaling, and TNFA signaling via NFκB, which are critical in promoting cell proliferation, survival, and chronic inflammation during the transition to gastric cancer." (PMID 40445003, 2025). "This suggests that combination therapies pairing KRAS G12C inhibitors with other approaches, such as chemoradiotherapy and immunotherapies, may help improve outcomes in gastric cancer, but high-quality clinical trials are further required." (PMID 40538856, 2025).
gastric cancer (continued). "Molecular subtyping plays a critical role in guiding combination therapy, as evidenced by the use of Trastuzumab combined with chemotherapy as the standard treatment for HER2-positive gastric cancer, as well as emerging strategies targeting BRAF mutations, KRAS mutations, and MSI-H/dMMR status." (PMID 41361128, 2025). "Understanding the cellular origin of KRAS-driven transformation is crucial for human gastric cancer, as different stem cell populations may give rise to distinct tumor subtypes with varying clinical behaviors." (PMID 40673273, 2025). "In addition, the results regarding KRAS gene status in colorectal and gastric cancer aligned with the Hardy–Weinberg equilibrium." (PMID 39673361, 2024). "Samples without HPV or EBV infection showed a high KRAS heterozygote mutation rate in colorectal and gastric cancer patients." (PMID 39673361, 2024). "At the same time, analysis of ferroptosis-related genes associated normal tissue and gastric cancer tissues screened out 19 FerDEGs: ten of them, i.e., TLR4, KRAS, HSF1, was highly expressed and nine of them, i.e., MUC1, PROM2, MT1G, were lowly expressed in tumor tissues." (PMID 36936437, 2023). "Therefore, these predicted herbs and herbal ingredients have great potential to improve the prognosis of gastric cancer patients by acting on the targets TLR4 and KRAS, and provide alternative options and direction for anti-gastric cancer herbal research." (PMID 36936437, 2023). "Also, according to the KG, both calcium and rap1 signalling pathways have other gene/protein associations such as ERBB2, KRAS and CDH1, which are further associated with the gastric cancer disease." (PMID 34181736, 2021). "We identified KRAS as a target of miR193b and found evidence that it could be negatively regulated by this miRNA in gastric cancer." (PMID 32596290, 2020). "As a tumor suppressor in gastric cancer, miR193b is negatively regulated by the activated Akt pathway and could decrease cell viability, inducing apoptosis, by targeting KRAS." (PMID 32596290, 2020). "Therefore, development of alternative therapies will be significant for treatment of KRAS mutant gastric cancers." (PMID 32486290, 2020). "Few studies exist that consider the importance of KRAS amplifications in gastric carcinoma." (PMID 32571252, 2020). "However, the expression level of KRAS in HER-2 gastric cancer cell lines was higher than that in the SKBR3 cell line." (PMID 30959742, 2019). "Moreover, a newly published study using gene-set enrichment analysis (GSEA) reported that in gastric cancer patients, GGT was significantly associated with EMT, KRAS, SRC and PKCA signaling pathways, which are involved in cancer progression and metastasis." (PMID 31664937, 2019). "In all 34 gastric cancer samples, neither KRAS nor NRAS mutation was detected, and only 1 sample (2.9%) was detected to have a mutation in BRAF exon 15 codon 600 600Glu." (PMID 30416987, 2018). "KRAS/NRAS/BRAF mutations were not significantly related to patients' age analyzed by Student's t-test or gender analyzed by Chi-square test in gastric cancer." (PMID 30416987, 2018). "The main purpose of this study is to investigate the mutation status and distribution of KRAS/NRAS/BRAF in Chinese colorectal and gastric cancers, and to explore the histopathological changes and related immunohistochemical marker changes caused by these mutations." (PMID 30416987, 2018). "The kinase ALPK2 is also reported to be under-expressed in gastric cancer and may be downregulated by oncogenic KRAS." (PMID 29100308, 2017).
gastric cancer (continued). "The pronounced reduction in phosphorylation of ERK1 and ERK2 after knockdown of the type I IGF receptor in KRAS-mutant SNU-1 gastric cancer cells is consistent with primary activation of their Ras/Raf/MAP-kinase pathway being dependent upon stimulus through the IGF signal transduction system." (PMID 27437872, 2016). "KRAS-addicted and BRAF-impaired gastric cancer cells were particularly susceptible." (PMID 27437872, 2016). "Furthermore, NVP‐BKM120 inhibited mTOR downstream activation, but induced the phosphorylation of AKT and ERK in KRAS mutant gastric cancer cells." (PMID 26715098, 2016). "MiR-181c was shown to directly target KRAS and exhibited a weak expression in gastric carcinoma." (PMID 26646588, 2016). "In addition, KRAS was shown to be targeted by miR-181a in oral squamous cell carcinoma, by miR-181c in gastric carcinoma, and by miR-181d in glioma." (PMID 26646588, 2016). "The detection of more frequent KRAS mutations within distal non-diffuse carcinomas in our dataset when using this subclassification further supports pathologic classification of gastric cancers based on location and histotype." (PMID 25656989, 2015). "Interestingly, even in a panel comprising KRAS mutant and wild type gastric cancer cell lines, EXO1 showed higher expression in KRAS mutant cell lines (YCC16 and AGS) when compared to wild type cells (KATOIII)." (PMID 24147022, 2013). "Together, these findings suggest for the first time that the dual inhibition of PI3K and STAT3 signaling may be an effective therapeutic strategy for KRAS mutant gastric cancer patients." (PMID 22159814, 2012). "In this study, we examined the efficacy of NVP-BKM120, a pan-class I PI3K inhibitor in human gastric cancer cells and hypothesized that the combined inhibition of PI3K and STAT3 would be synergistic in KRAS mutant gastric cancer cells." (PMID 22159814, 2012). "PI3K blockade in combination with STAT3 inhibitors may benefit patients with gastric cancer exhibiting oncogenic KRAS." (PMID 22159814, 2012). "KRAS amplification has been observed before in 5% of primary gastric cancers." (PMID 21781349, 2011). "Our results provide a molecular basis for the overactivation of KRAS, and suggest that the activation of KRAS downstream signaling events may promote gastric cancer cell proliferation." (PMID 19545448, 2009). "Using DGS, we identified KRAS as a gene that is amplified in human gastric cancer." (PMID 19545448, 2009). "The similar phenotypes between KRAS activation and PTEN loss reflect the convergent effects of these alterations on PI3K/AKT and MAPK signaling pathways, both of which are frequently dysregulated in human gastric cancer and promote epithelial proliferation and survival." (PMID 40673273, 2025). "This KRAS amplification is frequently found in CIN-type gastric cancer (GC; 14.3%) and esophageal adenocarcinoma (10.4%)." (PMID 36752207, 2023). "Interestingly, a novel KRAS mutation, not present in the primary tumor sample, was detected in the ascitic fluid of one gastric cancer patient (GC3)." (PMID 34336700, 2021). "Thus, our results suggest that the Akt-miR193b-KRAS axis may act as a mechanism affecting apoptosis in gastric cancer cells." (PMID 32596290, 2020). "No KRAS or NRAS mutation was found in gastric cancer in this study." (PMID 30416987, 2018). "We further demonstrated that SCRS data amplified by either MDA or MALBAC from a gastric cancer cell line could accurately detect gastric cancer CNVs with comparable sensitivity and specificity, including amplifications of 12p11.22 (KRAS) and 9p24.1 (JAK2, CD274, and PDCD1LG2)." (PMID 26251698, 2015). "In a previous high-throughput profiling of gastric cancers using OncoMap v3, percentage of samples with mutation was 38.2%, which is slightly higher than our incidences and the most frequent mutations were PIK3CA mutations (14.5%) followed by KRAS genes (7.7%) and PTEN (2.5%)." (PMID 22723903, 2012).
gastric cancer (continued). "Thus, our result suggests that dual inhibition of PI3K and STAT3 signaling may be an effective therapeutic strategy for KRAS mutant gastric cancer patients." (PMID 22159814, 2012). "Because we could show that combined treatment of NVP-BKM120 and AG490 caused synergistic inhibition of proliferation and induction of apoptosis in KRAS mutant gastric cancer cell lines, SNU-1 and SNU-601, we next examined their effects alone and in combination on signaling pathways." (PMID 22159814, 2012). "Our results showing that overexpressed wild-type KRAS is involved in the activation of downstream signaling pathways that govern cell proliferation indicate that the amplification of KRAS might be of clinical significance in predicting response to cetuximab or to panitumumab in gastric cancer." (PMID 19545448, 2009). "All three KRAS WT–amplified gastric cancer cell lines, MKN1, HuG1-N, and KE-39, have previously been shown to have an elevated KRAS protein level and to be dependent on KRAS for proliferation." (PMID 39711431, 2025). "Although HER2 is a well-established oncogene in breast and gastric cancers, it has recently gained recognition as a clinically significant biomarker in approximately 3–5% of CRLM, particularly among KRAS/NRAS wild-type tumors." (PMID 40805233, 2025). "BI-2493 dosed orally at 90 mg/kg twice daily induced durable tumor regressions in the MKN1 KRAS WT–amplified (CN = 12.7, TGI = 140%) gastric cancer model." (PMID 39711431, 2025). "The gastric cancer genome is characterized by focal amplification of oncogenes, including receptor tyrosine kinases, such as ERBB2 (HER2), EGFR, ERBB3, VEGF-A, KRAS/NRAS, MET, JAK2, and PD-L1/PD-L2." (PMID 38733489, 2024). "In a prior study, the KRAS proto-oncogene of the MAPK/ERK pathway was found to boost the transcriptional activity of GLI1 and the expression of SHH pathway target genes in gastric cancer." (PMID 36900220, 2023). "For instance, CSNK2A1 promotes gastric cancer invasiveness via the PI3K-Akt-mTOR signal pathway; CSNK2A1 is a mediator of MEK/ERK inhibitor resistance in KRAS (G12C) mutant LC cells; CSNK2A1 is a promising new prognostic marker for renal cell carcinoma." (PMID 35266446, 2022). "When we assessed the expression status of individual gastric cancer oncogenes (e.g., CEACAM6, EGFR, MET, CCND1, and KRAS) among the tumor epithelial clusters, the EpiInt1 tumor epithelial cluster exhibited the largest increase." (PMID 34642171, 2022). "In gastric cancer, miR-143 indirectly downregulates the expression of the human epidermal growth factor receptor (HER2), which is an upstream molecule of KRAS, by silencing DEAD/H-box RNA helicase 6 (DDX6)." (PMID 36233210, 2022). "In this arm, 25 KRAS mutant, KRAS-amplified, or MEK-signatured gastric cancer patients received second-line chemotherapy with docetaxel and selumetinib." (PMID 35406545, 2022). "After screening for oncogenes or suppressor genes, KIT, KRAS, and ERBB2 were significantly higher in gastric cancer ECs." (PMID 35755820, 2022). "Among the 90 gastric cancers, 10 cancers had gene amplification of one of ERBB2, KRAS, PIK3CA, and MET." (PMID 34873204, 2021). "As for gene amplifications, gastric cancers with current and past infection also had similar frequencies of ERBB2 amplification (9% and 3%; p = 0.398) and KRAS amplification (2% and 3%; p = 1.000)." (PMID 34873204, 2021). "In gastric cancer cells, FEZF1 enhances proliferation and tumorigenic by binding to and activating Kirsten rat sarcoma viral oncogene homolog (KRAS)." (PMID 31281667, 2019). "Amplification of seven oncogenes: HER2, EGFR, FGFR1, FGFR2, MET, KRAS and IGF1R has been identified in gastric cancer." (PMID 27437872, 2016).
gastric cancer (continued). "More specifically, reports in gastric cancer and melanoma provide evidence for the direct role of CXCL1 (a CXCR2 ligand) in regulating the protein levels of KRAS." (PMID 26771140, 2016). "Mutational activation and/or amplification of several oncogenes such as ErbB, KRAS, PIK3CA, MET, and MYC has been documented in gastric cancer." (PMID 25945346, 2015). "Furthermore, the ectopic expression of miR-433 and miR-127 in gastric cancer cell lines HGC-27 inhibits cell proliferation, cell cycle progression, cell migration and invasion by directly interacting with the mRNA encoding oncogenic factors KRAS and MAPK4 respectively." (PMID 23880861, 2013). "To investigate KRAS activity in gastric cancer cells, we analyzed the amount of GTP-KRAS in cells using an in vitro pull-down assay." (PMID 19545448, 2009). "KRAS is a negative predictor of metastatic colon cancer, whereas Her2neu is a positive predictor of advanced gastric cancer." (PMID 38496894, 2024). "Our work points out the need for a deeper genomic and biological characterization of KRAS status in tumours, such as gastric cancer, where this is not routinely evaluated." (PMID 38261067, 2024). "Indeed, one patient with HPD had KRAS amplification, which has been previously reported in patients HPD in a cohort of patients with gastric cancer." (PMID 33466719, 2021). "The 37 gastric cancer cell lines, which includedeight KRAS mutant cell lines (AGS, SNU601, SK4, SNU1, NCC24, SNU668, YCC2 and NCC59) in this study also showed similar results in that KRAS mutant cell lines had higher sensitivity to BI-2536 and volasertib." (PMID 32486290, 2020). "KRAS, PI3K and EGFR proteins are connected within a common signal transduction pathway, highlight the importance of the EGFR/MAPK pathway for the development of gastric cancer." (PMID 32698506, 2020). "In addition, the expression levels of downstream molecules such as KRAS, AKT, and ERK were up-regulated in MKN-7 and KATO-III cells compared with those of the other gastric cancer cell lines examined." (PMID 30959742, 2019). "Additionally, the expression of YAP1, FOXM1, KRAS, and BATF genes were decreased in gastric cancer cells by treatment of UA." (PMID 31547587, 2019). "EMT, KRAS, SRC and PKCA pathways may be the key signaling pathways in the GGT signaling in gastric cancer." (PMID 28404903, 2017). "For absence of NRAS, KRAS and BRAF mutation, SGC7901 and BGC823 gastric cancer cells were relative resistance to AZD6244 in vitro." (PMID 26567773, 2015). "Furthermore, CagA participates in cell signaling by activating the PIK3CA and KRAS pathways, ERK (MAPK), and MEK/ERK and JAK1 signaling pathway in gastric cancer cells." (PMID 23431236, 2013). "Since previous research demonstrated that STAT3 is required in KRAS-driven oncogenic transformation, we hypothesized that dual inhibition of PI3K and STAT3 would be effective in KRAS mutant gastric cancer cell lines." (PMID 22159814, 2012). "This study evidences previously observed perturbations of the KRAS, ERBB2, EGFR, MET, PIK3CA, FGFR2 and AURKA genes in gastric cancer and suggests some of the targeted therapies approved or in clinical development would be of benefit to 11 of the 50 patients studied." (PMID 21781349, 2011). "Immunoblot analysis of RAS proteins revealed that the expression of KRAS was increased in KRAS-amplified gastric cancer cells (HSC45, SH101P4 and MKN1), while neither NRAS nor HRAS were highly expressed (data not shown)." (PMID 19545448, 2009).